TNF (tumor necrosis factor)
Diseases named in the same sentence as TNF in open-access papers (continued):
Sharing a sentence is not in itself a finding about the gene and the disease.
periodontitis (continued). "In periodontitis-induced inflammation, α- and β-amyrins pretreatment at 5 mg kg−1 significant reduced TNF-alpha, the gingival myeloperoxidase and thiobarbituric acid-reactive substances, retarding acute inflammation in rat model." (PMID 33800018, 2021). "TNF-α, one of the essential pro-inflammatory cytokines in periodontitis patients, has been regarded as a potential biomarker for diagnosis of a periodontal disease." (PMID 35046930, 2021). "The concentrations of IL-1β, IL-6, and TNF-α were higher in periodontitis patients than in healthy controls." (PMID 34592963, 2021). "At the same time, it also alleviated the inflammatory response induced by TNF-α in periodontitis and other diseases, which is consistent with our results." (PMID 33833684, 2021). "After the periodontitis model establishment for 1 week, significantly increased mRNA expression of IL-1β, TNF-α, and IL-6 was observed in the IL-17 and IFN-γ groups than in the NS group (p < 0.05)." (PMID 34395635, 2021). "TNF-α, IL-1β, and IL-6 are the most important inflammation markers of periodontal disease, and its increase has been very well explained in periodontitis as a response to infection with the periodontal pathogens (Porphyromonas gingivalis, etc.)." (PMID 33746772, 2021). "Exposure of PBMCs to H2S triggered statistically significant higher levels of IFN-γ, IL-6, IL-17, and TNF-α secretion, both in the healthy group and in the periodontitis group." (PMID 34408814, 2021). "Three studies only assessed the serum IgG levels of the oral bacteria associated with periodontopathic biofilms; one study evaluated periodontitis by clinical parameters and also assessed pro-inflammatory cytokines levels (IL-1, IL-6, and TNF-α) in serum." (PMID 34108875, 2021). "Overall, we demonstrated that injection of Exo-TNF significantly decreased TRAP-positive osteoclasts in the mouse periodontitis model." (PMID 33359765, 2021). "We also found that the TNF-α mRNA expression was significantly increased in the periodontitis group compared to that in the control group." (PMID 34481478, 2021). "TNF-α, one of the most critical inflammatory factors in the progress of periodontitis, is mainly produced by activated macrophages, natural killer cells, T lymphocytes, and B lymphocytes." (PMID 32089705, 2020). "F. alocis, a member of the genus Filifactor, is not only present at the site of periodontitis but has also been shown to induce the production of inflammatory cytokines such as TNF-α, IL-1β and IL-6 in vitro." (PMID 33121117, 2020). "The level of TNF-α is elevated in the gastrointestinal tract of CD patients, as well as in the gingival crevicular fluid of periodontitis patients." (PMID 32164696, 2020). "The used TNF-α concentration (10 ng/ml) was clearly higher than in the GCF of periodontitis patients (up to 100 pg/ml)." (PMID 32423044, 2020). "In this study, PGFE inhibited the production of TNF-α, IL-1β, and IL-6, which are the major cytokines involved in periodontitis induced by PG-LPS, as well as the pro-inflammatory mediators NO and PGE2." (PMID 33287198, 2020). "One would like to be able to predict which patients with both RA and periodontitis would benefit from which TNF inhibitor." (PMID 33193432, 2020). "The IPA analysis also showed the validated HLADRB4 and ITGB2 genes both downregulated in Periodontitis patients (group P), interacting via TNF on the same network of cellular compromise, inflammatory response, and infectious diseases." (PMID 32424199, 2020). "In the current study, we aimed at identification of the expression pattern of TNF and HNRNPL related immunoregulatory (THRIL) and p50-associated COX-2 extragenic RNA (PACER) lncRNAs in the periodontitis." (PMID 32426538, 2020). "It has been reported that the average level of TNF-α in the gingival crevicular fluid (GCF) of periodontitis patients increases up to 9.5 ng/ml." (PMID 32089705, 2020).
periodontitis (continued). "In another study, the salivary macrophage inflammatory protein-1α, MM8, IL-1β, IL-6, prostaglandin E2 and TNF-α levels were reported to correlate with gingivitis and periodontitis development." (PMID 32646009, 2020). "proved that there is a significant additional value when anti-TNF combined to PDT is used to treat periodontitis compared to patients only receiving periodontal treatment or only using anti-TNF-α." (PMID 33193432, 2020). "The study is aimed at evaluating the effect of curcumin gel on serum levels of micronutrients (zinc, copper, and magnesium) and proinflammatory cytokines (IL-1β and TNF-α) in chronic periodontitis patients." (PMID 33083489, 2020). "Previously, higher possibilities of the DNA methylation located in specific loci of the TNF-α promoter gene as detected from human gingiva with periodontitis." (PMID 33376453, 2020). "In contrast to these results, others have shown that glycine contributes to inflammation by promoting toll-like receptor 2 to release increased levels of TNF-α, and upregulating bone resorption stimulators prostaglandin E2 and cyclooxygenases in periodontitis." (PMID 33552029, 2020). "Peripheral neutrophils secrete excessive IL-1β, IL-8, IL-6, and tumor necrosis factor-α in patients with periodontitis." (PMID 32698486, 2020). "Both HIF-1α and TNF were increased in gingival crevicular fluid both in chronic and in aggressive forms of periodontitis." (PMID 32831635, 2020). "This degradation is induced by proinflammatory cytokines such as IL-1β and TNFα, suggesting that these enzymes play an important role in the pathogenesis of periodontitis." (PMID 33294463, 2020). "In contrast, gingival fibroblasts treated with TNF-α showed significant reduction in the expression of adiponectin receptors as well as periodontal tissues from severe periodontitis patients compared to healthy ones." (PMID 32410876, 2020). "Antagonizing TNF-α using infliximab reduces expression of sclerostin and RANKL in osteocytes and the alveolar bone loss in diabetic rats with periodontitis." (PMID 32708317, 2020). "The pro-inflammatory cytokines IL-1β and tumor necrosis factor alpha (TNF)-α were frontrunner targets in the quest for molecular biomarkers of periodontitis activity." (PMID 33343358, 2020). "To understand the mechanistic effect of RSV on periodontitis-associated atherogenesis, we investigated the in vitro effect of RSV on various effect of TNF-α, a major proinflammatory cytokine for periodontitis and atherogenesis." (PMID 32286430, 2020). "More recently, a pre-clinical study observed an increase in inflammatory response and osteoclastogenesis in Goto-Kakizaki rats with ligature-induced periodontitis via TNF production." (PMID 32841254, 2020). "In the current study, we investigated the role of TNF and HNRNPL related immunoregulatory (THRIL) and p50-associated COX-2 extragenic RNA (PACER) lncRNAs in periodontitis." (PMID 32426538, 2020). "In our periodontitis and AD rat models, the levels of TNF-α and IL-6 in the hippocampus, and IL-1 and IL-6 in the cerebral cortex of the Lig+AD group were significantly higher than those of the AD group." (PMID 32614834, 2020). "Systemically, periodontitis increased circulating levels of pro-inflammatory cytokines, and primed bone marrow monocytes to produce elevated tumour necrosis factor-alpha (TNFα)." (PMID 30794103, 2020). "SRP was effective in reducing IL-1β total amounts in both moderate and deep sites (p < 0.001 for Grade C and p < 0.05 for Grade B, respectively) and TNF-α levels in deep sites (p < 0.05) of both periodontitis groups." (PMID 33218047, 2020). "Liraglutide significantly decreased periodontitis-induced iNOS and TNF-α gene expressions by 92% and 72%, respectively, in the gingiva." (PMID 33274238, 2020).
periodontitis (continued). "Several studies have found hypomethylation profiles within the interferon (IFN)-γ, IL-6, and TNF-α promoters, which was associated with increased IFN-γ, IL-6, and TNF-α transcription in gingival biopsies from patients with periodontitis." (PMID 33343358, 2020). "TNF plays a key role in chronic inflammation and, notably, in bone destruction observed in diseases such as RA, periodontitis, and periprosthetic osteolysis." (PMID 33133025, 2020). "Periodontitis increased inflammatory cell infiltration, macrophage accumulation, and gene expressions of tumor necrosis factor-α and inducible nitric oxide synthase in the gingiva, all of which were ameliorated by liraglutide." (PMID 33274238, 2020). "This overview presented promising results that anti-TNF therapy is beneficial in the treatment of both RA and periodontitis by improving periodontal parameters of RA patients." (PMID 33193432, 2020). "In fact, TNF-α and IL-6 are correlated with the clinical indicators of periodontitis severity as demonstrated by previous studies." (PMID 32509226, 2020). "HGFs were selected for use in the present study because they are the group of cells that are most highly affected by TNF-α and IL-1β in periodontitis." (PMID 32410860, 2020). "In conjunction, these data suggested that TNF-α and IL-17 are the cytokines most involved in the systemic response of experimental hyperglycemia and periodontitis, and consequently were the main targets of immunomodulation." (PMID 32841254, 2020). "Patients with severe periodontal disease had higher levels of TNF-α in the blood circulation, and the cytokines TNF-α, IL-6 and IL-1β are insulin antagonists, which play an important role in the pathogenesis of periodontitis." (PMID 32634783, 2020). "In ligature-induced periodontitis animal study, the expression of TNF-α in periodontal tissues is also higher in Goto-Kakizaki rats (type 2 diabetes model) than that of the normoglycemic Wistar rats." (PMID 32089705, 2020). "The levels TNF-α and IL-32 in gingival crevicular fluid and saliva were higher in chronic periodontitis patients, and then after treatments, these two biomarkers decreased." (PMID 33383828, 2020). "The association between tumor necrosis factor-alpha (TNF-α-308G/A, -238G/A, -863C/A, -1031T/C, and -857C/T) polymorphism and either chronic (CP) or aggressive (AgP) periodontitis susceptibility was conflicting." (PMID 32899013, 2020). "TNF-α and IL-1β are key pro-inflammatory cytokines that are involved in the pathogenesis of periodontitis and decrease wound healing and regeneration." (PMID 32024893, 2020). "The authors concluded that in the obese rat model, periodontitis increased the systemic LGI thereby upregulating the gene expression for hepatic levels of TNF-α and CRP and for IL-6 and CRP in the adipose tissue." (PMID 32486269, 2020). "The level of several other salivary cytokines, IL-6, IL-8, IL-17A, and tumour necrosis factor α (TNF- α) have been shown to be affected by periodontitis progress." (PMID 32646009, 2020). "Periodontitis as an inflammatory disease has been known to increase the levels of proinflammatory cytokines, including IL-1α, IL-1β, IL-6, and TNF-α." (PMID 33383828, 2020). "In this high activity scenario, the reduction in IL-1β in both moderate and deep sites and TNF-α in deep sites of both periodontitis groups suggests a role for these cytokines in the disease process." (PMID 33218047, 2020). "Yang et al27 found that inflammatory factors involved in periodontitis development, such as TNF‐α and IL‐1β, increased the proliferation ability of PDLSCs in vitro, which is consistent with the findings in this study." (PMID 31930698, 2020). "A decrease in the M1/M2 macrophage ratio was shown to inhibit alveolar bone resorption in mouse periodontitis models, while root resorption promoted by an increased M1/M2 macrophage ratio and high levels of TNF-α was observed in rats after 7 days of OTM." (PMID 32923485, 2020).
periodontitis (continued). "Similar heterogeneity of DNA methylation within individual promoters and site-specific differences between healthy donors and patients with periodontitis have been observed for the TNF and IFNG genes analyzed by pyrosequencing." (PMID 33256844, 2020). "IL6, IL6R, IFNG, PTGS2, SOCS1, and TNF were identified as candidate genes that have been assessed for DNA methylation in periodontitis." (PMID 32867386, 2020). "For immunological parameters, the result showed a significant increase in serum mean levels of Il-1β and TNF-α in chronic periodontitis patients (A and B groups) as compared to healthy control subjects." (PMID 33083489, 2020). "Studies showed that higher levels of IL-1β and TNF-α both in gingival crevicular fluid and PICF are associated with periodontitis and peri-implantitis, although there are contradictory results." (PMID 33111201, 2020). "In previous studies, PG-LPS was shown to be a major pathogenic factor of chronic periodontitis that stimulates PDL cells to produce pro-inflammatory factors, such as TNF-α and IL-1β, causing the destruction of the alveolar bone." (PMID 33287198, 2020). "These increased values were significantly correlated with parameters for periodontitis (% sites with bleeding, periodontal pockets ≥6 mm and pocket suppuration) and several inflammatory markers (IL-6, IL-10, TNF-α)." (PMID 30962800, 2019). "Addition of anti-RANKL and anti-TNF-α antibodies induced a dose dependent inhibition of the osteoclast formation in the periodontitis group." (PMID 30941138, 2019). "It has been broadly reported to induce host cells like oral epithelial cells to produce a wide range of proinflammatory cytokines, including tumor necrosis factor-α (TNF-α), interleukin-6 (IL-6) and interleukin-8 (IL-8), promoting periodontitis progression." (PMID 31684930, 2019). "In summary, we report here for the first time that activation of PTEN is necessary for inhibition of inflammation and alveolar bone loss, which suppresses both processes via inhibiting the IL1 and TNF-α pathways in periodontitis." (PMID 31886238, 2019). "In periodontitis, TNF-α is one of the key signals initiating several signaling pathways leading to chemotaxis of other inflammatory cells, tissue destruction and osteoclast formation." (PMID 31752295, 2019). "This was confirmed by the reduced expression of TNF and IL-1β in the gingiva of animals with specific-deletion of Dkk-1 in osteocytes submitted to periodontitis." (PMID 31921182, 2019). "During the development of periodontitis, neutrophils release matrix metalloproteinase and proinflammatory cytokines including TNF-α, CCL2, and IL-6." (PMID 31781234, 2019). "In periodontitis, TNF-α and IL-1β are actively present and are secreted by monocytes and macrophages, resulting in effects on the bone remodeling pathway." (PMID 31316593, 2019). "Inflammatory macrophages produce and secrete a large group of cytokines (IL-1β, IL-23, IL-6, tumor necrosis factor (TNF)-α) and enzymes (MMPs) that take part in osteoclastogenesis and collagen degradation in periodontitis." (PMID 31370168, 2019). "In particular, they produce pivotal pro-inflammatory cytokines in periodontitis such as IL-1β, IL-6 and TNF-α in response to bacterial challenge with the key periopathogen P. gingivalis through the NFκB and MAPK signaling pathways." (PMID 31848404, 2019). "Persistently increased levels of various pro-inflammatory cytokines (e.g., TNF-α and IL-6) have been well documented in RA and periodontitis, and several cytokine-targeting therapies are successfully used in RA treatment." (PMID 31072030, 2019). "Anti-TNF-α treatment also decreased osteoclast formation in patients with RA, periodontitis, and Gaucher's disease." (PMID 30941138, 2019). "Experimental periodontitis studies have shown that cytokines like IL-1 and TNF-alpha induce osteoclastogenesis via the RANKLRANK-OPG pathway." (PMID 30810635, 2019).
periodontitis (continued). "Periodontitis is a prevalent chronic inflammatory disease due to the host response (IL-1β, IL-6, TNF-α and IL-17A) to oral bacteria such as Porphyromonas gingivalis." (PMID 31848404, 2019). "An ELISA confirmed that the increased serum TNF-α level observed in periodontitis induced rats was significantly attenuated in PDT treated rats." (PMID 31160615, 2019). "LPS can induce the NF-κB signaling pathway activation to generate M1-related cytokines such as IL-6, TNF-α, IL-1β, and nitric oxide (NO) in macrophages during the progression of periodontitis." (PMID 31022963, 2019). "In contrast, the concentration of TNF-α used in our study was markedly higher compared to those measured in GCF in periodontitis (up to 100 pg/mL)." (PMID 31847340, 2019). "Periodontitis-challenged group expressed a significant increase in the mRNA levels of TNF-α (P<0.001), IL-1β (P<0.0000001), COX-2 (P<0.000004), iNOS (p< 0.007), RANK (P<0.036), and RANK-L (P<0.05), when compared to naive group." (PMID 31682614, 2019). "Some biomarkers for periodontitis, such as tumor necrosis factor-alpha, C-telopeptide pyridinoline cross-links of type I collagen, and receptor activator of nuclear factor kappa-B, are sensitive to salivary collecting techniques." (PMID 31216300, 2019). "In periodontitis, there is an increase in the production of proinflammatory mediators, such as IL-1β, TNF-α, IL-6, IFN-γ, and the levels of acute-phase proteins, such as CRP." (PMID 35919481, 2019). "Pivotal inflammatory cytokines in periodontitis, namely IL-1β, IL-6, TNF-α and IL-17A, mediate both periodontal inflammation and alveolar bone resorption." (PMID 31848404, 2019). "This initial hit triggers destructive events of periodontitis, such as increased production of bone-resorptive cytokines (IL-6, IL-1, TNF-α) and tissue-destructive proteinases (MMPs)." (PMID 31540277, 2019). "Gingival tissues in patients with periodontitis show greater increases in pro-inflammatory cytokines, such as IL-1, IL-6, IL-8, and TNF-α, as well as other inflammatory mediators, compared to gingival tissues in healthy individuals." (PMID 29401750, 2018). "Peripheral blood mononuclear cells (PBMCs) from patients with chronic periodontitis have been shown to produce large amounts of inflammatory cytokines including IFNγ and TNFα and differentiate to osteoclasts with high resorption activity by RANKL alone." (PMID 30158833, 2018). "There is affirmation to suggest that TNF-α gene plays an important role in the pathogenesis of periodontitis as it is a potent immunological intermediator with proinflammatory properties." (PMID 29449347, 2018). "TNF-α levels are increased in the gingival cervicular fluid in periodontitis and this cytokine is found in higher levels in the inflamed periodontal tissues compared with healthy periodontal tissues." (PMID 29449347, 2018). "T2DM is associated with higher serum levels of inflammatory mediators such as interleukin-1β and tumor necrosis factor-α and the local overproduction of these cytokines is a major contributor to alveolar bone destruction in periodontitis." (PMID 29548317, 2018). "For example, vitamin D has been reported to be able to inhibit the activity of some cytokines related to periodontitis and dementia by decreasing IL-6, IL-8, and TNF-α expression." (PMID 30618721, 2018). "Periodontal treatment can also successfully reduce circulating levels of TNF-α, CRP in patients with DM associated with periodontitis; however, research about the impact of successful long-term periodontal treatment does not exist and should be done." (PMID 30356347, 2018). "Our results were consistent with those of previous reports showing that CVL inhibited TNF-α expression in LPS-activated human monocytes and in a rat model of periodontitis and also inhibited NO expression in LPS-activated mouse macrophages." (PMID 30186288, 2018). "IL-1 and TNF-α not only enhance inflammation but also promote bone resorption, a major concern in periodontitis." (PMID 29507865, 2018).